TGFB1 (transforming growth factor beta 1)
Diseases named in the same sentence as TGFB1 in open-access papers (continued):
Sharing a sentence is not in itself a finding about the gene and the disease.
breast tumor (continued). "Firstly, we could confirm that transforming growth factor β1 (TGFβ1) secreted from breast tumor cells is a paracrine mediator of tumor-stroma interaction leading to the activation of autophagy in the stroma component fibroblasts." (PMID 28515430, 2017). "TNFα and TGFβ1 are both expressed in many tumors and, as our findings so far indicate, act in cooperativity to promote the pro-inflammatory phenotype of MSCs, which also prevail in breast tumors." (PMID 28553282, 2017). "In addition, we found that TGFβ1 can induce miR-21 expression in a dose-dependent manner, while SSA significantly attenuated TGFβ1-induced miR-21 expression in breast tumor cells." (PMID 26769851, 2016). "IGF1R and TGFB1 were significantly overexpressed in the highest AHR-expressing group, but only in ERα-positive breast tumors (p = 0.0088 and p = 0.0035, respectively)." (PMID 29320557, 2018). "In our primary breast tumor specimens, correlation between mtDNA content and the expression of ESRP1 (ρ = 0.25, P < 0.001), SNAI1 (ρ = 0.23, P < 0.001) and TGFB1 (ρ = 0.18, P < 0.01) was statistically significant after correction for multiple testing." (PMID 27081694, 2016). "Significantly higher TGFB1 and TGFB3 mRNA levels and lower TGFBR2 mRNA levels were observed in the primary breast tumours compared with their matched normal tissues." (PMID 26703884, 2015). "Together, these findings suggest that tumors containing high levels of TNFα and TGFβ1 are enriched with the inflammatory and tumor-promoting mediators CCL2, CXCL8 and Cox-2, and that all three inflammatory mediators are coregulated in human breast tumors." (PMID 28553282, 2017). "The mean expression level of TGFB1 gene was higher in sporadic compared with familial BC (2.30 ± 0.29 vs 1.55 ± 0.21; p= 0.04), whereas the mean level of ATM transcript was lower in sporadic BC compared to breast tumors with a family history (0.72 ± 0.15 vs 2.72 ± 0.56; p= 0.001)." (PMID 28881597, 2017). "Thus, in the node-negative population, the upregulation of PAi-1 by TGFβ1 might constitute an early event that promotes further progression of breast tumours." (PMID 16404434, 2006). "Using previously published protocols, we induced migration of a non-metastatic human breast tumor cell line, MCF-7 by TGFβ1." (PMID 26769851, 2016). "In addition, the expression levels of p-Smad2, p-Smad3, and Smad4 in the nucleus of MCF-7 breast tumor cells were measured by immunofluorescence microscopy, and we found that SSA could reduce the level of p-Smad2/3 in the nucleus with or without the presence of TGFβ1." (PMID 26769851, 2016).
Sepsis (182 papers, 2007 to 2026). Sepsis is defined as life-threatening organ dysfunction caused by a dysregulated host response to infection. "We believe that future studies need to evaluate the role of TGFβ1 and female sex hormone as a possible combined protective mechanism in sepsis." (PMID 37875957, 2023). "On the other hand, histopathological damage in liver and lung was ameliorated by injection of mesenchymal stem cells with high TGFβ1 expression 6 h after induction of sepsis by CLP." (PMID 37875957, 2023). "TGFβ1 has been shown to be important to the development of sepsis-related organ failure and the inflammatory response to infections." (PMID 21573017, 2011). "The role of TGFβ1 in sepsis is controversial, but it is a regulator of inflammatory function." (PMID 37875957, 2023). "Furthermore, the activation of TGFβ1/SMAD pathway has been verified to facilitate sepsis-induced acute lung injury." (PMID 35264055, 2022). "TsES also have a regulatory function and increase IL-10 and TGFβ1, which could regulate the inflammatory response during sepsis." (PMID 25054155, 2014). "Cell surface expression of TSP-1 on platelets is increased in sepsis and could activate the anti-inflammatory cytokine transforming growth factor beta (TGFβ1) affecting outcome." (PMID 21573017, 2011).
liver disease (180 papers, 2009 to 2026). "Despite the extensive research conducted on the relationship between transforming growth factor-beta 1 (TGF-β1) polymorphisms and levels and the onset and development of liver disease, there are still certain gaps that need to be addressed." (PMID 37525796, 2023). "In this work, the distribution frequency of three singlenucleotide polymorphism (SNP) variants of the Tgfb1 gene,namely rs1800469, rs1800470, and rs1800471, was studied in children withend-stage liver disease (ESLD)." (PMID 37908775, 2023). "In this work, we studied thedistribution of the three most significant Tgfb1 polymorphisms(rs1800469, rs1800470, and rs1800471) in pediatric patients with congenital andhereditary liver diseases." (PMID 37908775, 2023). "It was worth noting that SPP1 and TGFB1 genes are not only associated with congenital (and childhood) liver disease, but also with adult liver disease." (PMID 34095116, 2021). "Concurrently, elevated H3K4me3 levels at the Tgfb1 locus have been documented in human liver disease specimens." (PMID 41274506, 2025). "The transforming growth factor-beta 1 (TGF-β1) is a cytokine that plays an important role in the pathogenesis of liver disease." (PMID 37525796, 2023). "Capillin extracted from Artemisia capillaris spica inhibits apoptosis induced by transforming growth factor-beta 1 (TGF-β1), which is observed in various inflammatory liver diseases." (PMID 34680529, 2021). "Therefore, inhibiting the TGFβ1/SMAD3/NOX4 pathway is an effective strategy to reduce ROS generation in liver diseases, and the correlative work deserves further study." (PMID 40060764, 2025). "We therefore hypothesized that the inhibition of TGFβ1/SMAD3/NOX4 pathway could be a potential mechanism by which GSH enhances ADSC engraftment efficiency in liver diseases." (PMID 40060764, 2025). "However, the relationship between Nrf2 and TGFβ1 in the regulation of liver diseases is rarely reported." (PMID 33707345, 2021). "In addition, NOX4 was shown to be especially critical for TGFβ1-triggered apoptotic death of hepatocytes thus contributing to development of liver disease." (PMID 26035647, 2015). "Further, in light of the previous report that ROS induces production of cytokine, such as TGFβ1, for promotion of hepatic fibrogenesis, Nef could facilitate liver disease progression by enhancing secretion of the cytokine via ROS production." (PMID 24911518, 2014). "In a study on metabolic dysfunction-associated steatotic liver disease (MASLD), the new definition of NAFLD, organoid models exhibited varying cellular responses under different induction conditions (oleic acid, palmitic acid, and transforming growth factor beta 1 (TGF-β1)." (PMID 41359105, 2025). "Although the complete upstream signaling pathways of NOXs remain unknown, TGFβ1/SMAD signaling pathway, a well‐known regulator in the progression of liver diseases, has been shown to regulate NOX4/ROS pathway in a SMAD3‐dependent manner." (PMID 40060764, 2025). "Literature mining has further revealed an inverse correlation between miR-122 and TGFβ1 levels in patients with liver diseases, including non-alcoholic fatty liver disease, primary biliary cholangitis, HCC, and viral hepatitis." (PMID 37566034, 2023). "In this model, exposure of liver slices to the well-characterised autocrine stimulators of fibrosis, TGFβ1+ PDGFβ, robustly induces fibrogenesis, thus, pharmacological inhibition of UCHL1/HIF signalling in this model is highly relevant for translation to human liver disease." (PMID 38808772, 2024).
Ureteral obstruction (180 papers, 2008 to 2026). Obstruction of the flow of urine through the ureter. "Wild-type or TGFβ1-overexpressing mice with unilateral ureteral obstruction (UUO) were treated with an activin A neutralizing antibody." (PMID 36717814, 2023). "Interstitial fibrosis that developed following unilateral ureteral obstruction was significantly attenuated by a peptide inhibiting TSP1/latent TGFβ1 interaction, and this was associated with a reduction in active TGFβ1 and Smad activation." (PMID 36909183, 2023). "In mice with pro-fibrotic injury induced by ureteral obstruction, upregulation of Tgfb1 was accompanied with downregulation of Epas1 and Epo in injured kidneys and myofibroblasts, which were reversed by ALK5 inhibitor SB431542." (PMID 34724959, 2021). "An expression of TGFβ1 showed a strong correlation with fibrosis of smooth muscle layer in rats with unilateral ureteral obstruction." (PMID 27727327, 2016). "Conversely, an introduction of TGFβ1 siRNA delays the development of fibrosis in a unilateral ureteral obstruction (UUO) model with concomitant down-regulation of type 1 COL and PAI-1." (PMID 24691097, 2014). "We examined the effect of curcumin on RIF in vivo and in vitro, via a unilateral ureteral obstruction (UUO) model as well as its effect on the transforming growth factor beta 1 (TGF-β1)-stimulated and the LPS-stimulated inflammatory responses in the human renal proximal tubular cells." (PMID 32866059, 2020). "Based on the results showing the linkage between Nrf2 and TGFβ1 signaling, we hypothesized that Nrf2 could have a potential role in protecting the kidney in unilateral ureteral obstruction." (PMID 30130014, 2018). "After unilateral ureteral obstruction, downregulation of DRP1 improves mitochondrial function and reduces the proliferation of fibroblasts by hypoxia-stimulated transforming growth factor beta 1 (TGFβ1), a key inducer of fibrosis in the renal proximal tubules." (PMID 39335773, 2024). "In other global kidney injury models (e.g., unilateral ureteral obstruction [UUO]), increased TGFβ1 production in the kidney alters the ratio of transcription factors Smad2 and Smad3, favoring activation of fibrosis programs." (PMID 32227630, 2020). "These include TGFb1-induced in vitro fibrosis models and in vivo CKD models such as the TGFb1 overexpressing mice model and the unilateral ureteral obstruction (UUO) model." (PMID 32235450, 2020). "In addition, Wang and collaborators have revealed that miR-29a attenuates kidney fibrosis in Unilateral Ureteral Obstruction (UUO) mice by inhibiting fibrotic proteins and TGFB1." (PMID 38256206, 2024).
glaucoma (171 papers, 2008 to 2025). Increased pressure in the eyeball due to obstruction of the outflow of aqueous humor. "They target various genes and pathways, including mTOR, MEK/ERK, and TGFβ1 processing, contributing to the prevention of oxidative damage in glaucoma." (PMID 37834147, 2023). "High levels of TGFβ1 and TGFβ2 isoforms have been reported in different eye fluids including AH and vitreous humor (VH) of glaucoma patients." (PMID 33832461, 2021). "High levels of TGFβ2 were detected in the aqueous humor of patients with glaucoma, and TGFβ1 and β2 are also expressed in local cells (conjunctival epithelium and fibroblasts) in the filtering bleb tissue." (PMID 34769176, 2021). "The experimental animals that were treated with a dose of 50 μl of 1% OMT demonstrated the most notable fall in the TGFβ1 levels (p < 0.001, p < 0.001) when compared to the glaucoma control and standard groups, respectively." (PMID 35252223, 2021). "The TGFβ signaling pathway is of particular interest in glaucoma, since functional studies have shown the role of elevated TGFβ1 signaling in inflammation, senescence and ECM deposition in TM cells, lamina cribrosa (LC), and aqueous humor of glaucomatous eyes." (PMID 32825664, 2020). "This evidence suggests a crucial role for DNA methylation in glaucoma onset as well as in regulating TGFβ1 gene expression as a novel therapeutic approach." (PMID 31976085, 2019). "Moreover, in patients with glaucoma there is an increased expression of TGFβ1 and a reduction in anti-fibrotic factor Rat-sarcoma (RAS) protein activators like RASAL1." (PMID 38474069, 2024). "The preclinical findings obtained from this study implicate an evident role of the TGFβ1 isoform in the progression of glaucoma, which might contribute to the various pathological alterations seen in patients with glaucoma." (PMID 35252223, 2021). "TGFβ1 has also been found to be elevated in the AH, along with TGFβ2, of patients with clinically active glaucoma and has also been found to be involved with the activation of thrombospondin-I via induction through dexamethasone (DEX) in TM cells, resulting in stress conditions." (PMID 35252223, 2021). "We hypothesise that the hypoxic environment seen in glaucoma may contribute to the disease fibrosis by changing the global methylation profile of the cells, which subsequently alters the expression of TGFβ1 and RASAL1." (PMID 27124111, 2016). "We suggest that TGFβ1 and RASAL1 have an interacting role in glaucoma, which could perpetuate the associated fibrosis." (PMID 27124111, 2016). "Therefore, any alteration in TGFB1 levels may affect the AH outflow facility, and thereby contributing to increase in IOP which is the main risk factor for glaucoma." (PMID 33832461, 2021). "Strong staining of TGFβ1 was observed for PXG, the TGFβ1 expression was maximal in the endothelial space in early stages, and eyes with glaucoma had maximal expression in epithelial or sub-epithelial layers." (PMID 33914756, 2021). "In this study we found TGFβ1 and MMP-9 protein concentrations were high in PXG but MMP-9 activity was reduced in eyes with glaucoma." (PMID 33914756, 2021). "The levels of TGFβ-1, IL-8, and SAA correlated positively with each other, with IOP, and the number of glaucoma medications." (PMID 29675026, 2018). "DNA methylation was increased in both glaucoma TM cells, and in normal TM cells subjected to hypoxia, and 5-aza was able to ameliorate the increased TGFβ1 and decreased RASAL1 observed in glaucoma TM cells." (PMID 27124111, 2016). "TGFβ1 has been shown to be the primary isoform in PXFG, and the main site of pseudoexfoliation syndrome deposits in glaucoma occur in the TM region." (PMID 27124111, 2016). "Further, we wished to establish the relationship between TGFβ1, RASAL1 and DNA methylation in TM cells in glaucoma." (PMID 27124111, 2016).
glaucoma (continued). "These include transforming growth factor β2 (TGFβ2) in primary open angle glaucoma (POAG) and TGFβ1 and connective tissue growth factor (CTGF) in pseudoexfoliation glaucoma (PXFG)." (PMID 27124111, 2016). "Indeed, high levels of IL8, VEGFA, PDGF, TGFB1, and TGFA have been found in AH of glaucoma patients." (PMID 37569323, 2023). "Our results showed that there is an increase of TGFβ1 and MMP-9 which was consistent in each ocular tissue in the later stages of PXF which may have role in the pathogenesis of glaucoma." (PMID 33914756, 2021). "Another group found the levels of IL-8, TGFβ-1, TNF-α, and SAA to be significantly increased in POAG and pseudoexfoliation glaucoma (PEXG) patients compared with controls, while levels of IL-6 were significantly decreased in both glaucoma groups compared with controls." (PMID 29675026, 2018). "We also found an increased expression of MMP-2, MMP-3, MMP-9, TGFβ-1, and TGFβ-3 in eyes with JIAU, independent of the presence of glaucoma." (PMID 29675026, 2018).
viral infection (168 papers, 2005 to 2026). "TGFB1 gene region polymorphisms can also alter TGFβ1 transcription, expression, and function, affecting viral infection susceptibility and disease progression." (PMID 38970443, 2024). "Transforming growth factor-beta 1 (TGF-β1) secreted by tumor cells promotes OV infection in CAFs, while high levels of fibroblast growth factor 2 (FGF2) make tumor cells more susceptible to viral infection." (PMID 39337402, 2024). "Thereby, these findings indicated that the miR-663a-TGFB1 axis might be play a critical role in occurrence and development of virus-induced cancers, but its function on the other viruses infection remains to be investigate." (PMID 35864512, 2022). "In addition to cellular immunity, TGFβ1 can disrupt humoral immunity in viral diseases." (PMID 38526562, 2024). "GAS6 mRNA was decreased in the MSCs stimulated with recombinant IL-1β, TNF-α, TGFβ1 (produced by MSC), and PDGBB (produced by endothelial cells) at 6 h, while poly I:C, known to mimic viral infections, increased GAS6 expression." (PMID 37958918, 2023).